IL1B (interleukin 1 beta)
Diseases named in the same sentence as IL1B in open-access papers (continued):
Sharing a sentence is not in itself a finding about the gene and the disease.
tendinopathy (continued). "Therefore, a positive feedback loop might exist as an IL-1β-mediated mechanism through mechanical loading in tendinopathy, and ER-mediated signaling pathways might also be involved." (PMID 30296306, 2018). "Consistent with clinical findings, IHC showed significantly higher expression of IL-1β in the Td-Inj and Td-Sut groups compared with the sham group in all time points (P < 0.05), suggesting that IL-1β may serve as a critical inflammatory mediator in tendinopathy." (PMID 41258071, 2025). "In conclusion, we found that the NLRP3/ASC-inflammasome controls the production of IL-1β, meanwhile, another ASC-dependent inflammasome is required to produce IL-18 in tendinopathy induced by sterile tissue degradation of the extracellular collagen matrix." (PMID 39468985, 2024). "In the severe tendinopathy group, there was higher expression of MMP9 and IL-1β in media containing PRP." (PMID 36769065, 2023). "As macrophages are also involved in the progression of tendinopathy, advanced experiments were conducted to explore the roles of ADMSC-derived EVs on macrophages treated with IL-1β." (PMID 36604715, 2023). "Upregulation of inflammatory mediators (e.g., IL1β, IL1, IL6, and tumor necrosis factor-α) strongly suggests that inflammation is a key process in tendinopathy." (PMID 35689230, 2022). "Inflammatory mediators (IL-1β, IL-6 and TNF-α) have been reported to be highly expressed in tendon diseases and accelerate the progression of tendinopathy." (PMID 35458235, 2022). "The expression of IL-21R is affected in the first phase of tendinopathy as seen in culture after chemical challenge with TNF-α, and IL-1β." (PMID 34863223, 2021). "The cytokine IL‐1β has been shown to enhance the cleavage and release of COMP from tendon explants 31, with fragments being present in the early stage of tendon disease." (PMID 30739342, 2019). "IL-1β, IL-17, and TNF-α may contribute to tendinopathy by impairing the biological activity of tenocytes." (PMID 39850191, 2024). "In particular, the interleukin-1 beta (IL-1β) regulates inflammatory mediators and matrix metalloproteinases (MMPs) which degrade the extracellular matrix (ECM) and contribute to the development of tendinopathy and even tendon rupture." (PMID 33807327, 2021). "Given that inflammation is an important external stress related to tendinopathy, we provided evidence that the proinflammatory factors IL-1β activated by mechanical loading were the upstream negative regulators of miR-337-3p in rTDSCs in vitro." (PMID 31065679, 2020). "Although the key cytokines in tendon disease have not yet been fully defined, family members of the interleukin-1 (Il-1) family, in particular Il-1β, can trigger catabolic degradation of the ECM via the activation of MMPs, thereby contributing to the progression of tendinopathy." (PMID 31052237, 2019). "For example, PDGF levels were lower in women with tendinopathy but not in males with tendinopathy, and IL-1β showed a non-significant trend toward being lower in the female tendinopathy group as well." (PMID 26925234, 2016). "Other potentially interesting biomarkers for musculoskeletal diseases, such as tendinopathy, include TNF-α, interleukin 1 beta (IL-1β), basic fibroblast growth factor (bFGF), interferon gamma (IFN-γ), platelet derived growth factor BB (PDGF-BB) and vascular endothelial growth factor (VEGF)." (PMID 26925234, 2016). "Physical activity was correlated with TNF-α, PDGF-BB and IL-1β to varying extents for control subgroups, but not for the female tendinopathy group." (PMID 26925234, 2016). "Significance testing for PDGF-BB (p = 0.023) and IL-1β (p = 0.059) levels between women with and without tendinopathy remained unchanged." (PMID 26925234, 2016). "There was a non-significant trend for IL-1β to be lower in women with tendinopathy (p = 0.059)." (PMID 26925234, 2016).
tendinopathy (continued). "Interestingly, IL-1β was also found to activate the PI3K/Akt signaling pathway leading to the activation/nuclear translocation of NF-κB, further supporting the key role of this transcription factor as an effective molecular target for the treatment of tendinopathies." (PMID 39108992, 2024). "Second, we focused on the central role of NF-kB in inflammation and in tendinopathy, which is activated by TNF rather than IL-1β." (PMID 37600349, 2023). "Interestingly, proinflammatory and catabolic cytokines such as interleukin-1 beta (IL-1β), tumor necrosis factor alpha (TNF-α), and interferon gamma (IFN-γ) have been immunolocalized in horses with tendinopathy but not in healthy horses." (PMID 40284884, 2025). "Finally, correlations between TNF-α and IL-1β, and between TNF-α and PDGF-BB were seen for all women but not when control and tendinopathy groups were examined separately." (PMID 26925234, 2016).
Fever (56 papers, 2008 to 2025). Body temperature elevated above the normal range. "Other pro-inflammatory cytokines, such as TNF-α, IL-1β and IL-6, are thought to be associated with fever and multi-organ dysfunction in HLH." (PMID 40842582, 2025). "Previous studies have linked HP-PRRSV-induced fever to IL-1β, potentially explaining the lower incidence and duration of fever observed in the MV group compared to the Vac group." (PMID 39161459, 2024). "Fever is known to be caused by several endogenous pyrogens such as interleukin-1β (IL-1β) and IL-6, interferon-α (IFN-α), tumor necrosis factor-α (TNF-α), macrophage protein-1, and prostaglandins such as PGE2 and PGI2." (PMID 33747115, 2021). "IL-1β is commonly referred to as an endogenous pyrogen and is generally associated with pyrexia." (PMID 18700003, 2008). "In patients under therapy with BRAF/MEK inhibitors but also by in-vitro experiments it could be demonstrated that the BRAF inhibitor dabrafenib induces IL-1beta (IL-1β) to a greater extent than the other BRAF inhibitors which are associated less frequently with pyrexia." (PMID 36006943, 2022). "Plasma levels of inflammatory cytokines (PGE2, IL-1β, and IL-6) were significantly elevated (p < 0.05) in V. harveyi-challenged seahorses under thermal gradient conditions (fever group) compared to those maintained at constant temperature (no fever group)." (PMID 40508975, 2025). "For example, ellagic acid relieved pyrexia by inhibiting yeast-induced overproduction of IL-1β, PGE2, and metabolic biomarkers PE (16:0/20:4), PC (18:2/15:0), and sphingolipid." (PMID 38675434, 2024). "In a lipopolysaccharide-induced fever rodent model, researchers observed a lower fever and lower pro-inflammatory cytokines IL-1β and TNFα in animals pre-treated with KD compared to controls, although ketone body measures were not included." (PMID 37936721, 2023). "The selected genes, il1b, tnfa, and il6, showed more robust local induction of gene expression under dynamic fever conditions (TD group), where fish had been allowed to swim freely through the established 10°C temperature gradient within the ATPT." (PMID 36917159, 2023). "If this is the case, once a sufficient level of fever is reached, the heat itself would inhibit the production of IL-1β, limiting the drive for pyrexia and limiting the potential for overwhelming inflammation." (PMID 37190098, 2023). "In conclusion, these data suggest that the evaluation of IL-1A, IL-1B and IL-18 gene SNPs can add useful information on the clinical course of patients affected by Mediterranean Spotted Fever, even if further confirmatory studies will be necessary." (PMID 36551320, 2022). "IL-1β then induces fever and creates an inflammatory environment to prevent HTNV invasion, and causes increased vascular permeability by activating IL-1 receptors, which plays an important role in HFRS pathogenesis." (PMID 35538453, 2022). "Among inflammatory cytokines, IL-1β is a main actor of pyrexia and anti-bacterial response and is highly secreted by the adipose tissue." (PMID 34437647, 2021). "The incidence of pyrexia involves many mediators, such as interleukins IL-6, IL-1β, IL-8, and TNF-α, as recorded in previous studies." (PMID 34641376, 2021). "IL-6 is regarded as an endogenous mediator of LPS-induced fever and IL-1β can initiate and enhance the inflammatory response." (PMID 31842849, 2019). "This is consistent with prior observations that UCP-1-dependent thermogenesis is dispensable for IL-1β- and LPS-induced fever." (PMID 29746591, 2018). "IL-1Ra is an anti-inflammatory cytokine that can attenuate IL-1-induced fever (by neutralizing IL-1β)." (PMID 27459266, 2016). "Referring back to the fever which occurred in the infected chickens in this study, we think that this fever has been attributed to the endogenous pyrogenic action induced by the high IL-1β expressed in these chickens." (PMID 27347679, 2016).
Fever (continued). "IL-1β mediates the migration of leukocytes, induces fever, and promotes the activation and polarization of T cells." (PMID 26865111, 2016). "Lonicerae japonicae flos has antipyretic effects in dry yeast-induced rat fever model and the IL-1β-induced fever model in New Zealand rabbits, possibly due to the expression of prostaglandin E2 receptor EP3 at the preoptic area of hypothalamus (POAH) neurons." (PMID 26257818, 2015). "Hyperthermia and fever are initiated following exposure to exogenous (bacteria, toxin) or endogenous pyrogens (pro-inflammatory cytokines (IL-1β, IL-6 and tumor necrosis factor-α (TNF-α))." (PMID 22971439, 2012). "Similarly, Atlantic salmon (Salmo salar) infected with infectious pancreatic necrosis virus (IPNV) exhibited behavioral fever, increasing their preferred temperature and upregulating pro-inflammatory cytokines (IL-1β, IL-6, TNF-α)." (PMID 40508975, 2025). "This marked production of potent endogenous pyrogens such as IL-1β, IL-6 and TNF-α, can interact directly with the anterior hypothalamus, through a hierarchy of neural structures, and raise the temperature setpoint, causing fever." (PMID 39928662, 2025). "In our experiments, it was confirmed that SHL could reduce the pro-inflammatory cytokines TNF-α, IL-6, and IL-1β in LPS-induced fever rats in order to play an antipyretic and anti-inflammatory effect." (PMID 35837285, 2022). "The occurrence of pyrexia involves numerous nerval routes and factors, such as IL-1β and PGE2." (PMID 35458665, 2022). "IL-18 and IL-1β are pro-inflammatory cytokines primarily produced by activated macrophages and both overlap in many functions but differ in signaling pathways with IL-1β being highly involved in pyrexia." (PMID 33228660, 2020). "Furthermore, it is understood that IL-6 acts in concert with IL-1β as an endogenous pyrogen during LPS-induced fever." (PMID 30674283, 2019). "Like IL-1β, IL-6 induces the production of acute phase proteins, pyrexia and sickness behaviour." (PMID 24134207, 2013). "Thus, fever suppresses IL‐1β and IL‐10 gene expression in Mtb‐stimulated MDM." (PMID 40667841, 2025). "However, we did observe significant increases in IL-1β transcription after prolonged exposure to pyrexia (53 h), which could be attenuated by preceding hypothermia." (PMID 31871429, 2019). "Additionally, antibodies against IL-1β only partially reduced LPS-induced fever in rats." (PMID 24870145, 2014). "In mice fever models, ADHP1 demonstrated marked antipyretic efficacy through dual suppression of pro-inflammatory cytokines (IL-1β, TNF-α) and prostaglandin biosynthesis." (PMID 40633473, 2025). "The fever group had significantly increased serum levels of TNF-α, IL-1β, IL-6 and PTGS2 (p < 0.05, p < 0.01) compared to the control group." (PMID 40430430, 2025). "Compared with the NG, the mRNA expressions of TNF-α, IL-6, IL-1β, NF-κB, TRPV4, and HSP70 in the MG were significantly upregulated (P < 0.01), indicating that the expression of mRNA was enhanced under fever conditions." (PMID 40356990, 2025). "Fever was induced using turpentine, an exogenous pyrogen that stimulates endogenous pyrogens such as TNF-α, interferon-gamma (IFN-γ), IL-1β, and IL-6 to initiate the synthesis of PGE2." (PMID 41245555, 2025). "The results demonstrated that the levels of ET-1, ICAM-1, TNF-α, IL-1β, MMP-9, NF-κB, NO, and TXB2 in yeast-induced fever in the model group rats were significantly higher than in the control group (P < 0.001)." (PMID 35178159, 2022). "The activities of IL1β and IL6 are similar to TNF-α, including the induction of pyrexia and the production of acute phase proteins." (PMID 31918707, 2020). "Fever is typically induced by the production of pro-inflammatory cytokines, such as TNF-α and IL-1β, during LPS immune challenge." (PMID 30841603, 2019). "The level of IL-1β and PGE2 increases significantly in the animal fever model; this finding implies that the levels of these factors could be used to evaluate the antipyretic effect of drugs." (PMID 35458665, 2022).
Fever (continued). "Remarkably, during behavioural fever at 48 hpi, Il1β, Il6, and Tnfα1 protein levels were higher than those in the no-fever individuals." (PMID 34445566, 2021). "Consistent with our secondary hypothesis, we demonstrated higher levels of IL-8 and IL-1β in saliva of children with seizures compared with age-matched fever controls and showed a positive correlation between HHV-6 viral load and IL-1β level in saliva." (PMID 30344507, 2018). "The il1β and tnfα1 cytokines mRNAs expression patterns were detected only in individuals that developed behavioural fever, in stark contrast to what was found in the no-fever group." (PMID 34445566, 2021). "Moreover, warming to pyrexia resulted in a significant increase in IL-1β transcription in the noncooled OGD/R-injured group (53 h)." (PMID 31871429, 2019). "Therefore, the inflammation‐suppressive action of the bioactive components of Fevogrit could well be the primary mode of action of Fevogrit against LPS‐induced fever, as shown by the reduced levels and gene expression of TNF‐α, IL‐1β and IL‐6 in serum and hypothalamus, respectively." (PMID 39021318, 2025). "HMGB1 together with IL-1β, IL-8, IL-10, and MCP-1 can serve as biomarkers to identify children with ALL and fever or SIRS who should not receive antimicrobial treatment because the origin of their fever is not due to an infectious agent." (PMID 40868835, 2025). "Although Histoplasma infection stimulated the production of pyrogenic cytokines (i.e., IL-1β, IL-6, and TNF-α), pyrexia is not induced in mice." (PMID 29295913, 2018).
lung disease (55 papers, 2009 to 2025). "After further adjustment for traditional and HIV-related risk factors for lung disease, as well as cytokines (IL-1β, IL-10), the gut microbial dysbiosis index was independently associated with rapid lung function decline." (PMID 40557154, 2025). "IL-1β polymorphisms are present among PwCF and specific single nucleotide polymorphism (SNP) in the IL-1β gene have been associated with lung disease in CF." (PMID 40791588, 2025). "IL-1β alleles that enhance IL-1β expression are associated with increased risk of developing TB disease, more severe pulmonary disease, and poor treatment outcome." (PMID 30258448, 2018). "In support of this, inflammasome-activated IL-1β has been shown to play a major role in lung sterile inflammation induced by other nanoparticles associated with lung diseases." (PMID 26437452, 2015). "Among individuals with lung diseases caused by members of the M. avium complex, the IL-1β response and NLRP3 inflammasome activation are decreased in PBMCs, monocytes, and macrophages compared with those in healthy controls, indicating increased host susceptibility." (PMID 39511430, 2024). "The sputum of neutrophilic asthma and COPD patients contain elevated levels of extracellular DNA and increased gene expressions of NLRP3 and IL-1β, which correlate with the severity of lung disease." (PMID 40791588, 2025). "Airway epithelial cells undergoing necrosis release IL-1β through activation of the IL-1R-MyD88 signaling pathway that is known to induce neutrophilic inflammation in mice with CF-like lung disease." (PMID 40791588, 2025). "IL-1β is a pro-inflammatory cytokine that plays a key role in initiating the inflammatory response in pulmonary diseases." (PMID 40394619, 2025). "A line of several, in vitro and in vivo, studies suggest a role of inflammasome-mediated IL-1β activation in lung diseases including CF." (PMID 40791588, 2025). "The data summarized in this review article propose, however, that a self-perpetuating, positive feedback loop consisting of IL-1β and NETs represent a significant driving force behind CF lung disease progression." (PMID 40791588, 2025). "The highest significance was for IL-1β which is a key moderator of the initiation of the inflammatory response in lung disease." (PMID 36670409, 2023). "IL-1β is a pluripotent proinflammatory cytokine involved in various inflammation-related lung diseases." (PMID 37371919, 2023). "More specifically, blocking either IL-1β or IL-36γ after DA inhalation exposure is of particular interest in attenuating lung disease progression." (PMID 34941793, 2021). "Our findings bring new insight into how unresolved inflammation mediated by persistent IL-1β signals prevents cell fate transitions, resulting in impaired regeneration and eventually leading to lung diseases." (PMID 32750316, 2020). "Considering the proinflammatory function of IL-1β in the inflammatory process of various lung diseases, we then examined the mRNA and protein expression of IL-1β in lung tissue and BALF respectively." (PMID 28276511, 2017). "Nevertheless, other studies have reported associations between a number of cytokines, such as TNF-α, IL-1β, IL-6, IL17 and TGF-β1, and radiographic TB lung disease presentation." (PMID 27494953, 2016). "Activated macrophages derived from P2X7R−/− mice are unable to secrete the mature form of IL-1 family cytokines, including IL-1β and IL-18 and hence, these animals show reduced severity in models of acute inflammatory joint or lung disease." (PMID 26542019, 2015). "Since IL-1β has been related to a number of human diseases, including different pulmonary pathologies, and PM is known to increase the development of lung disease, it is crucial to increase the understanding of the pathways involved." (PMID 23509682, 2013).